EGFR (epidermal growth factor receptor)
Diseases named in the same sentence as EGFR in open-access papers (continued):
Sharing a sentence is not in itself a finding about the gene and the disease.
gastric cancer (continued). "Gefitinib has shown anticancer activity against gastric cancer which work through inhibiting epidermal growth factor receptor (EGFR)." (PMID 29618949, 2018). "This study identifies the gastric cancer-associated genes such as EGFR, KLF4, DNMT1 and AGO4 as candidates of ceRNA network in gastric cancer." (PMID 29719612, 2018). "EGFR and integrin β4 expression, proliferation and apoptosis of gastric cancer cells were assayed by indirect immunofluorescence, western blot, MTT and flow cytometry respectively." (PMID 29618949, 2018). "The EGFR expression level in gastric cancer is closely related to the incidence and development of gastric cancer, and it can provide a theoretical basis for the targeted therapy of gastric cancer positive for EGFR expression." (PMID 30087428, 2018). "Our previous study observed that the HECT E3 ubiquitin ligase NEDD4 is significantly correlated with tumor metastasis and required for migration and invasion signaling of EGFR in gastric cancer cells." (PMID 29455656, 2018). "The anti-EGFR antibody nimotuzumab is currently being investigated in phase 3 clinical trials in patients with EGFR-overexpressing advanced gastric cancer (AGC) (ENRICH study NCT01813253)." (PMID 28852882, 2018). "EGFR is highly expressed in gastric cancer tissues, and gastric cancer patients overexpressing EGFR are more likely to have distant metastases, and the tumors have a higher recurrence rate and a shorter survival period." (PMID 30524285, 2018). "This study aimed to investigate the ability of CT texture analysis to assess and predict the expression levels of immunohistochemical biomarkers, including E-cadherin, Ki67, VEGFR2 and EGFR, in gastric cancer." (PMID 30087428, 2018). "In the current study, we depict an individual with gastric cancer that harbored EGFR as well as MDM2 amplification who had indolent disease; the patient, however, showed explosive progression after being given the anti–PD-1 inhibitor nivolumab." (PMID 30148248, 2018). "Among the upregulated lncRNAs, Lnc00152 promotes proliferation in gastric cancer through the EGFR-dependent pathway." (PMID 29490660, 2018). "Our results suggest that different components of the EGFR signaling network are important regulators of the phenotypic and molecular behavior of gastric cancer cell lines in response to cetuximab treatment." (PMID 29237412, 2017). "The frequent overexpression of EGFR in gastric cancer generated particular interest in this RTK for targeted therapy." (PMID 29237412, 2017). "On the other hand, a lot of direct evidence has emerged the benefit of anti-HER3 agents in combination with EGFR tyrosine kinase inhibitors as well as anti-HER2 agents in gastric cancer." (PMID 28924391, 2017). "Then, anti-EGFR therapy has also received a great attention in esophageal or gastric cancer, and various anti-EGFR agents have been tested in randomized controlled trials." (PMID 29228748, 2017). "Overall, before disregarding EGFR as a possible target in gastric cancer, we should carefully identify patients with EGFR pathway activation and evaluate the effect of inhibition of this receptor in this context." (PMID 28915702, 2017). "In contrast, the EGFR/HER2 small-molecule inhibitor lapatinib showed only limited efficacy in treating advanced gastric cancer." (PMID 27933395, 2017). "We previously examined the effects of EGF and cetuximab treatment for 3 min on the expression and activation level of EGFR in gastric cancer cell lines." (PMID 29237412, 2017). "The aim of this update meta-analysis was to clarify the clinicopathologic and prognostic significance of human epidermal growth factor receptor(EGFR) expression in gastric cancer patients." (PMID 28199988, 2017). "The data suggested that EGFR was an indispensable molecular in the process of ACh stimulated gastric cancer cell proliferation." (PMID 28102288, 2017).
gastric cancer (continued). "For example, it is capable of inhibiting the epidermal growth factor receptor (EGFR) in gastric cancer cells which is involved in DNA synthesis and cell proliferation." (PMID 28208712, 2017). "In consequence, inhibition of EGFR in our gastric cancer model should inhibit these two downstream pathways in a cetuximab-sensitive cell line but not in a non-responder line." (PMID 29237412, 2017). "The Epidermal Growth Factor Receptor is amplified in around 5% of gastric cancers, characterized by poor prognosis." (PMID 28915702, 2017). "Recent reports indicated that EGF and its receptor EGFR were increased in some tumors, such as gastric cancer, and GBM, which further induced tumorigenesis, and stimulated cell proliferation and migration." (PMID 29254162, 2017). "Here, we evaluated the effects of EGFR signaling in gastric cancer cell lines to link the phenotypic behavior of the cells with their molecular characteristics." (PMID 29237412, 2017). "It has been reported previously that CTNND1, EZH2, BCL2L2, CDH2, VIM, and EGFR have positive correlation to proliferation, invasion, and poor prognosis of gastric cancer." (PMID 28694563, 2017). "In a total of 202 gastric cancer patients, Hisamatsu demonstrated that there was a positive relationship between p-Akt and EGFR, both of which were significantly correlated with DNA aneuploidy." (PMID 28938690, 2017). "To determine the association between PD-L1 and the EGFR/HER2 pathway, we examined the protein expressions of PD-L1 and molecules related to the EGFR/HER2 signaling pathway in seven gastric cancer cell lines." (PMID 28969039, 2017). "Here we show that EGFR in exosomes secreted from gastric cancer cells can be delivered into the liver and is integrated on the plasma membrane of liver stromal cells." (PMID 28393839, 2017). "In terms of the patient’s status, ten studies were designed for the unselected (whole) advanced gastric cancer patients and four studies were for the selected (EGFR-positive)." (PMID 27633381, 2016). "Helicobacter pylori‐increased IL‐8 promotes human gastric cancer cell proliferation through transactivation of EGF receptor (EGFR) by disintegrin and metalloproteinase (ADAM) activation." (PMID 26945908, 2016). "The addition of anti-VEGFR target drugs to chemotherapy for gastric cancer significantly improved outcome of OS, PFS, ORR, while anti-EGFR target drugs only led to improved outcome for OS and PFS in EGFR-positive gastric cancer." (PMID 27633381, 2016). "EGFR, a homodimer of ErbB1, is of particular importance in gastric cancer, as its level of expression is increased during the progression of tumor progression and is correlated with reduced overall survival." (PMID 26830684, 2016). "Downregulation of EGFR by an EGFR-specific shRNA lentiviral vector decreased cell proliferation and invasion of gastric cancer with induction of cell cycle arrest and apoptosis." (PMID 26700961, 2016). "Ectopic expression of CD24 in gastric epithelial cells augmented the expression of EGFR, while knockdown of CD24 in gastric cancer cells decreased the level of EGFR and cell migration velocity." (PMID 26830684, 2016). "Treatment of AGS cells with epidermal growth factor (EGF) induced a marked increase in AGS cell migration and invasion, suggesting that EGFR signaling is involved in gastric cancer metastasis." (PMID 27105510, 2016). "It indicated that anti-VEGFR target drugs can prolong the life time of patients with gastric cancer, but anti-EGFR drugs can only prolong the life time of the EGFR-positive patients with advanced gastric cancer." (PMID 27633381, 2016). "We recommended anti-VEGFR target drugs can be used for the whole patients with gastric cancer, and anti-EGFR drugs should be selected to EGFR-positive patients." (PMID 27633381, 2016). "The expression of VEGFR and EGFR was an independent prognostic indicator of worse outcome in gastric cancer patients." (PMID 27633381, 2016).
gastric cancer (continued). "In the present study, the fact that depletion of CD24 leading to low expression of EGFR in gastric cancer cells attracted our attention." (PMID 26830684, 2016). "In previous studies, EGFR gene amplification has been reported to be present in only 2.3–4.9 % of gastric cancers including all histological subtypes, whereas the reported numbers for HER2 gene amplification vary between 7 and 17 %." (PMID 27387915, 2016). "Taken together, these observations suggest that CD24 knockdown impairs EGFR function in gastric cancer cells." (PMID 26830684, 2016). "Analysis of gastric cancer specimens revealed a positive correlation between CD24 and EGFR levels and an association between CD24 expression and worse prognosis." (PMID 26830684, 2016). "Research data showed that the tumorigenesis and development of gastric cancer was closely related to receptor tyrosine kinases (RTKs), including EGFR and c-Met." (PMID 27147579, 2016). "Berberine was tested for its ability to enhance the antitumor effects of EGFR inhibitors in gastric cancer." (PMID 27738318, 2016). "In the present study, we investigated the relevance of EGFR expression in CD24 positive gastric cancer." (PMID 26830684, 2016). "To assess the effect of CD24 on total EGFR level, we transfected human gastric cancer cells SGC-7901 with control siRNA or siRNA for CD24." (PMID 26830684, 2016). "In a study, the role of DARPP-32 in mediating resistance to gefitinib, a small tyrosine kinase inhibitor specific for EGFR, was investigated in gastric cancer." (PMID 26872373, 2016). "Taken together, these findings demonstrate that RhoA function is necessary for CD24-mediated EGFR stability in gastric cancer SGC-7901 cells." (PMID 26830684, 2016). "Together, our results indicate that CD24 plays an important role in regulating EGFR and EGFR-initiated signaling in gastric cancer." (PMID 26830684, 2016). "Several mAbs as well as TKIs directed against EGFR have been evaluated in different settings for metastatic esophageal and gastric cancer." (PMID 26844548, 2016). "Collectively, these data suggest that CD24 modulates EGFR subcellular location in gastric cancer cells." (PMID 26830684, 2016). "A study with truastuzumab combined chemotherapy showed favorable efficacy of a 68 % response rate, 16 months of OS, and 7.8 months of PFS in EGFR-positive advanced gastric cancer." (PMID 27633381, 2016). "In this paper, we reported that GL-1196, as a small molecular compound, effectively suppressed the proliferation of human gastric cancer cells through downregulation of PAK4/c-Src/EGFR/cyclinD1 pathway and CDK4/6 expression." (PMID 27077843, 2016). "The anti-VEGFR drugs can improve the efficacy for the whole patients with unresectable advanced or recurrence gastric cancer and the anti-EGFR drugs can only improve the efficacy for the EGFR-positive patients." (PMID 27633381, 2016). "Another phenomenon we noticed here was that, in serum-starved conditions, CD24-knockdown cells had lower EGFR expression compared to control cells, and such difference was apparent before and after the gastric cancer cells were stimulated with EGF." (PMID 26830684, 2016). "A recent study has shown that TGFβ induces HBEGF shedding and EGFR transactivation through ADAM17 activation in gastric cancer cells." (PMID 27802351, 2016). "Recent studies also suggest that overexpressed EGFR in gastric cancer cells is efficiently targeted by HSP90 inhibitors for degradation." (PMID 26859680, 2016). "We here show that CD24 positively regulates the expression of EGFR in gastric cancer cells, and that expression of CD24 supports the EGFR-PI3 K/Akt and EGFR-ERK signaling pathway." (PMID 26830684, 2016). "Because the gastric cancer tissue samples we studied here were from China, we used the two gastric cancer cell lines derived from Chinese gastric carcinoma patients to study the regulation of EGFR by CD24." (PMID 26830684, 2016).
gastric cancer (continued). "EGFR has been identified widely expressed in a variety of tumors and about 20 % to 30 % of patients with gastric carcinoma overexpress EGFR." (PMID 27633381, 2016). "According to our previous report, the rs2293347 SNP in EGFR was extracted as a potential predictive factor of chemotherapeutic response in Japanese gastric cancer patients treated with fluoropyrimidine." (PMID 26475168, 2015). "A variety of techniques have been employed to investigate the frequency of EGFR copy number gain or amplification in esophago-gastric cancer, yielding a frequency of 6.25- 49 %." (PMID 26478746, 2015). "A potential benefit of EGFR amplified gastric cancers to anti-EGFR therapies deserves further evaluation in which, however, the frequent heterogeneity of amplification – 5/7 EGFR amplifications were heterogeneous in our patients - will have to be factored in." (PMID 25649416, 2015). "EGF has been shown to be a potent pro-migratory factor for a variety of cultured gastric cancer cells, and EGFR is highly expressed in gastric cancer." (PMID 25779663, 2015). "EGFR signaling pathways are frequently dysregulated in gastric cancer, thereby serving as attractive therapeutic targets." (PMID 25185971, 2015). "We used the Sequenom EpiTYPER assay to detect the methylation status of the EGFR promoter in normal and tumour tissues of 30 patients with gastric cancer." (PMID 25959250, 2015). "Since the assessment of EGFR expression using IHC is a well-established method, we used IHC to analyze EGFR expression in tumors from 167 gastric cancer patients with varying levels of ND after microarray experiments." (PMID 25154973, 2015). "In a recent preclinical study, 4 of 20 gastric cancer xenografts responded favorably to the anti-EGFR antibody cetuximab, two of which had EGFR amplification." (PMID 25649416, 2015). "We would, therefore, like to explore the clinical significance of EGFR genomic status in gastric cancer with ND in the near future." (PMID 25154973, 2015). "Even in our initial screening, FGFR2 expression, similar to that of NKX2.1 correlates well with that of EGFR expression in primary gastric cancer." (PMID 25154973, 2015). "Our immunohistochemical analysis of EGFR and HER2 also showed the similar those result, that EGFR expression had prognostic relevance for gastric cancer patients who underwent standard treatment." (PMID 25154973, 2015). "For this purpose, we selected 4 genes (HER2, CCND1, MYC and EGFR) with established relevance for gastric cancer, which were previously reported to be amplified." (PMID 25649416, 2015). "Ultimately, the EGFR was validated as such a candidate molecule in patients with primary advanced gastric cancer who underwent standard treatment (n = 167)." (PMID 25154973, 2015). "Epidermal growth factor receptor (EGFR) is a member of the receptor tyrosine kinases ErbB family and it is found to be overexpressed in gastric cancer." (PMID 25959250, 2015). "The EGFR has already been demonstrated to be a good target of molecular therapy against gastric cancer." (PMID 25154973, 2015). "In gastric cancer, overexpression of epidermal growth factor receptor (EGFR), human epidermal growth factor receptor 2 (HER2), and HER3 is correlated with poor prognosis." (PMID 26225765, 2015). "A meta-analysis of 7 studies concluded that EGFR expression correlates with decreased survival in gastric cancer." (PMID 25784931, 2015). "NTR1, β-catenin and EGFR expression in gastric cancer tissues and the adjacent normal tissues of 210 cases was detected by Immunohistochemistry." (PMID 26215716, 2015). "In this respect, it is interesting that EGFR genomic amplification has been previously reported in gastric cancer." (PMID 25154973, 2015). "In conclusion, we identified the EGFR gene as the reemerged molecule which explains the mechanism of aggression of advanced gastric cancer with high ND." (PMID 25154973, 2015).
gastric cancer (continued). "The limited benefit and high toxicity of multi-agent cytotoxic chemotherapies in esophago-gastric cancer have prompted investigation of targeted therapies, including those targeting EGFR and HER-2." (PMID 26478746, 2015). "By using controlled Fab-arm exchange, a set of BsAbs targeting EGFR and c-MET was generated to establish an accurate receptor quantitation of a panel of lung and gastric cancer cell lines expressing heterogeneous levels of EGFR and c-MET." (PMID 26260789, 2015). "A randomized phase III trial investigating the addition of nimotuzumab (a monoclonal antibody to EGF), to irinotecan as second line treatment of EGFR overexpressing gastric cancers is now ongoing (ENRICH, ClinicalTrials.gov identifier NCT01813253)." (PMID 25649416, 2015). "Pre-screening of EGFR status is frequently performed in lung and gastric cancers to determine the effectiveness of EGFR-targeted therapies including gefitinib and erlotinib." (PMID 26121470, 2015). "Here we observed that BGC-823 cells (an EGFR-rich human gastric carcinoma cell line) were resistant to the EGFR tyrosine kinase inhibitor, gefitinib." (PMID 25652880, 2015). "EGFR, another receptor tyrosine kinase is noted for its overexpression in some gastric cancers and trials employing the use of EGFR inhibitors are currently underway." (PMID 25025766, 2014). "Our previous studies followed up with a role for EGFR transactivation in tumor cells that enhanced proliferation of gastric cancer cells." (PMID 24887129, 2014). "In human oncology, the importance of the EGFR/HER-2/KRAS signalling pathway in gastric cancer is well established, and HER-2 testing is required before initiating therapy." (PMID 24454858, 2014). "Some potential molecular targets for therapy in gastric cancer have been reported in previous studies, such as EGFR (epidermal growth factor receptor), VEGF (vascular endothelial growth factor) and RON (recepteur d’origine nantais)." (PMID 27919040, 2014). "A number of clinical trials have also been conducted to test the usability of EGFR inhibitors in gastric cancer." (PMID 24728052, 2014). "The present study aimed to evaluate the prognostic significance of EGFR expression in patients with advanced gastric cancer." (PMID 24348859, 2014). "We unveiled that M. hyorhinis activates PI3K-AKT signaling in gastric cancer cells in an epidermal growth factor receptor (EGFR)-dependent fashion." (PMID 25505372, 2014). "This is in good agreement with existing data that show that both EGFR and HER2 are associated with poor prognosis in gastric cancer." (PMID 24728052, 2014). "In some respects, the association between EGFR GCN and treatment response resembles the findings of another EGFR family member, Her2, in gastric cancer." (PMID 24940619, 2014). "On the other hand chromosome 17 is rarely polyploid in gastric cancer, which indicates a different biological mechanism for EGFR and Her2 increase." (PMID 24940619, 2014). "Cetuximab, which targets human EGFR, has demonstrated promising results in treating advanced gastric cancer." (PMID 24758484, 2014). "In human oncology, the importance of the EGFR/HER-2/KRAS signalling pathway in gastric cancer is well established." (PMID 24454858, 2014). "In this study, although EGFR expression in patients with gastric carcinoma was 49% (40/81), in sporadic patients it was 30.9% (25/81)." (PMID 24348859, 2014). "The present study investigated the cytotoxic activity of CIK cells targeted by epidermal growth factor receptor (EGFR)/CD3 BsAbs against the gastric cancer cell line SGC7901 to analyze the effect of this therapeutic strategy against gastric cancer." (PMID 23833649, 2013). "The results of our study reveal an important link between PKM2 and E-cadherin during EGFR-stimulated gastric cancer cell motility and invasion." (PMID 23840737, 2013).